GJC3 (gap junction protein gamma 3)
Description:
One gap junction consists of a cluster of closely packed pairs of transmembrane channels, the connexons, through which materials of low MW diffuse from one cell to a neighboring cell.
Synonyms: Cx30.2; Cx31.3; GJE1; CX29
Tractability: Small molecule: a structure with a bound ligand is known. Antibody: UniProt places it where antibodies can reach, with medium confidence; UniProt predicts a signal peptide or a membrane-spanning region; its Gene Ontology location is reachable by antibodies, with medium confidence.
Gene: Protein-coding gene on chromosome 7 (99,923,266 to 99,929,620, reverse strand). Ensembl gene ENSG00000176402.
Subcellular location: Cell membrane; Cell junction, gap junction
Gene Ontology:
Molecular function: protein binding; gap junction channel activity; gap junction channel activity involved in AV node cell-bundle of His cell electrical coupling; identical protein binding
Biological process: AV node cell to bundle of His cell communication by electrical coupling; cell-cell signaling; cell communication; transmembrane transport
Cellular component: connexin complex; gap junction; myelin sheath; plasma membrane
Genetic constraint (gnomAD): Loss-of-function variants: 16 observed, 20.04 expected, observed/expected ratio (o/e) 0.8, 90% interval 0.54 to 1.21. The upper end of that interval is the gene's LOEUF score, 1.21, which puts it in group 5 of 6, group 1 being the genes least tolerant of losing a copy. Missense variants: 302 observed, 339.36 expected, observed/expected ratio (o/e) 0.89, 90% interval 0.81 to 0.98. Synonymous variants: 131 observed, 138.5 expected, observed/expected ratio (o/e) 0.95, 90% interval 0.82 to 1.09.
Homologues: Orthologues: chimpanzee GJC3 (99% identical), macaque GJC3 (96% identical), rabbit GJC3 (78% identical), dog GJC3 (75% identical), dog GJC3 (74% identical), pig GJC3 (71% identical), guinea pig GJC3 (68% identical), rat Gjc3 (61% identical), mouse Gjc3 (61% identical). Paralogues in human: GJC1 (38% identical), GJC2 (34% identical), GJA3 (33% identical), GJD2 (33% identical), GJA8 (33% identical), GJA10 (32% identical), GJA5 (31% identical), GJA9 (31% identical), GJA1 (31% identical), GJA4 (31% identical), GJB7 (28% identical), GJB1 (27% identical), and 8 more.
Diseases named in the same sentence as GJC3 in open-access papers:
GJC3 is named in the same sentence as 14 diseases in open-access papers, as found by Europe PMC text mining. Sharing a sentence is not in itself a finding about the gene and the disease. The quoted sentences say what the papers report.
hearing loss (10 papers, 2013 to 2023). "Mutations in connexin genes—Cx26 (GJB2), Cx30 (GJB6), Cx29 (GJC3), Cx31 (GJB3) and Cx43 (GJA1)—have been identified as the culprits for hearing loss with distinct pathological changes in the cochlea." (PMID 33917368, 2021). "A few rare mutations in GJC3 (Cx30.2/Cx29) and GJB3 (Cx31) have also been linked to hearing loss but it is unclear what role these connexins play and even where these connexins are localized in the auditory tract." (PMID 32300592, 2020). "Cx30 (GJB6), Cx29 (GJC3), Cx31 (GJB3), and Cx43 (GJA1) mutations can also cause hearing loss with distinct pathological changes in the cochlea." (PMID 26074771, 2015). "Site-specific mutations in COL1A1, GJC3, RRM2B, SALL4, and SALL1 cause otosclerosis ([MIM:120150]), delayed hearing sensitivity ([MIM:611925]), sensorineural deafness ([MIM: 604712]), hearing loss ([MIM:607343]) and ear dysplasia ([MIM:602218]), among other deafness-related disorders." (PMID 36803022, 2023). "We determined the cryo–electron microscopy structures of human connexin 31.3 (Cx31.3)/GJC3 hemichannels in the presence and absence of calcium ions and with a hearing-loss mutation R15G at 2.3-, 2.5-, and 2.6-Å resolutions, respectively." (PMID 32923625, 2020).
melanoma (2 papers, 2019 to 2025). A malignant, usually aggressive tumor composed of atypical, neoplastic melanocytes. "In three melanoma cell lines, we also showed the loss of GJA1/Cx43 and the differential expression of GJB1/Cx32, GJB2/Cx26, GJA3/Cx46 and GJC3/Cx30.2." (PMID 30717194, 2019). "Metastatic melanomas showed the loss of GJA1 (Cx43) protein, the increase in cytoplasmic GJB2 (Cx26), and the upregulation of both GJC3 (Cx30.2) and GJB1 (Cx32) through melanoma progression, compared to melanocytes." (PMID 40227837, 2025).
deafness (1 paper, 2023). An inherited or acquired condition characterized by the complete loss of the ability to hear from one or both ears. "We identified five predicted highly suspected deafness-associated genes, namely, COL1A1, GJC3, RRM2B, SALL4 and SALL1, in the available databases, including Ensemble and OMIM, indicating that they were correctly identified as deafness-associated genes." (PMID 36803022, 2023).
peripheral nervous system disease (1 paper, 2023). "A number of these, including connexin 26 (Cx26)/GJB2, Cx29/Cx31.3/GJC3, Cx30/GJB6, Cx32/GJB1, Cx36/GJD2, Cx43/GJA1, Cx45/GJC1 and Cx47/GJC2 are expressed in the central and/or peripheral nervous system and mutations in a number of these cause central and/or peripheral nervous system disease." (PMID 37189458, 2023).
GJC3 also shares sentences with these, for which no sentence is quoted: Hearing impairment (2 papers); peripheral neuropathy (2); auditory neuropathy (1); breast carcinoma (1); carcinoma (1); glioma (1); injury (1); ischaemic heart disease (1); otosclerosis (1); prostate tumor (1).